TNF (tumor necrosis factor)
Diseases named in the same sentence as TNF in open-access papers (continued):
Sharing a sentence is not in itself a finding about the gene and the disease.
tumor (continued). "The combination of decreased TNFα, IL-1β, and COX-2 found in the PDTC treated epidermis provides compelling evidence that Hr is capable of modulating epithelial inflammation via regulation of the NFκB pathway and thereby further contributes to tumor promotion." (PMID 22761871, 2012). "To evaluate this hypothesis we have measured the concentration of selected cytokines: TNF, IFNγ, IL-12 (p70), MCP-1, IL-6, and IL-10 in the tumor lysates and in the sera taken from mice at the time of their sacrifice." (PMID 23251384, 2012). "In such a setting, inflammatory cells that were recruited to the tumor site in response to chemokines such as CCL2 and CCL5 continue releasing the inflammatory cytokines TNFα and IL-1β, whose activities further promote the release of the cancer-related chemokines." (PMID 24213226, 2012). "Recombinant human TNF also promoted tumor implantation in the same xenograft models, but had no anti-tumor effect." (PMID 22296757, 2012). "The rationale for delivering TNF to the tumour site as a therapeutic approach is further supported by a clinical trial showing no clinical activity by TNF when administered systemically daily for 5 consecutive days in patients with androgen-independent PCa." (PMID 23326670, 2012). "We may speculate that when IGF-IR is silenced, TNF-α and IFN-γ secretion contributed to decreased tumor growth either priming T cell response, blocking tumor stroma or triggering tumor apoptosis." (PMID 22235273, 2012). "The antitumor activities of N1 neutrophils include expression of immune activating cytokines (TNF-α, IL-12, GM-CSF, and VEGF), T cell attracting chemokines (CCL3, CXCL9, CXCL10), lower expression of arginase, and a better capacity of killing tumor cells in vitro." (PMID 23217146, 2012). "These two cytokines are multifunctional and are produced mainly by activated macrophages and lymphocytes, although non-hematopoietic cells such as malignant cells or tumor stroma cells also synthesize TNF-α." (PMID 22235273, 2012). "Although TNF was secreted and biologically active, colonization levels of recombinant C. acetobutylicum were low, and sufficient amounts of TNF to combat the tumour cells were not secreted, and therefore no therapeutic benefits were observed." (PMID 22737166, 2012). "At the same time, serum levels of TNF, IFNγ, and MCP-1 were lower in mice bearing ADAM17-silenced tumors than mock-transfected ones, which is not surprising as serum levels of the cytokines usually correlate with the tumor size." (PMID 23251384, 2012). "In another study, TNF−/− but not wild-type mice failed to recruit NK cells to the peritoneum, the site where a variety of tumour cells including RM1 murine PCa, have been injected." (PMID 23326670, 2012). "In a tumor setting, this might be triggered by soluble cytokines (TNFα, FasL or TRAIL) in the tumor microenvironment." (PMID 22909995, 2012). "Moreover, potential secretion of TNFα, VEGF-A and TGF-β1 from primary tumours induced S100A8 and S100A9, which in turn stimulated the enrichment of other inflammatory chemo-attractants." (PMID 23157946, 2012). "In contrast, these same high avidity T cells produce multiple cytokines (IFNγ, IL-2, and TNFα) when transferred into tumor-bearing non-tolerant FVB/N mice." (PMID 22359647, 2012). "TNF-α activates multiple mitogen-activated protein kinase (MAPK) cascades in intestinal epithelial cells (IECs) leading to the secretion of interleukin 8 (IL-8), a neutrophil chemoattractant and an angiogenic factor with tumor promoting properties." (PMID 22988345, 2012). "Non-tumor-bearing EE mice showed a significant increase in adiponectin levels but no change in those of leptin, F2-isoprostanes, PGF2α, IL-6, TNF-α, PAI-1, and MCP-1 levels." (PMID 23272114, 2012). "Apart from the direct cytotoxic activity of TNF and IFNγ against MC38CEA cells, the cytokines may influence in vivo tumor growth also through modulating immune response." (PMID 23251384, 2012).
tumor (continued). "Hence we analyzed the secretion of IL-22, TNF-α and IFN-γ, each of which is known to contribute to certain forms of skin pathogenesis." (PMID 23056446, 2012). "In contrast to 125I-labeled SSLs, tumor retention of 125I-labeled arginine (the substrate of 125I labeling in SSLs) is not affected by TNF-α." (PMID 21378416, 2011). "Pro-inflammatory factors including TNF-alpha and LPS could induce AEG-1 in both tumor and non-tumor cells." (PMID 22060137, 2011). "Under such conditions, TNFα & IL-1β would not act on the tumor cells to promote the release of CCL2 & CCL5, leading to lack of associations between the two cytokines and CCL2 & CCL5." (PMID 21486440, 2011). "IL-12, TNF-α and IFN-γ are known to be effective anti-tumor cytokines." (PMID 22216160, 2011). "Although treatment with Doxil or 131I-labeled IgG in the absence of TNF-α retarded tumor growth and prolonged animal survival, the tumors always grew back." (PMID 21378416, 2011). "Moreover, our results suggest an important role for TNFα in breast malignancy, because the cytokine has substantial ability to promote progression-related processes by inducing EMT processes in the tumor cells." (PMID 21486440, 2011). "Macrophages can kill HPV-16 E6 but not E7-expressing tumor cells through tumor necrosis factor (TNF)-α and nitric oxide (NO)-dependent mechanisms." (PMID 24212964, 2011). "Such advantages could be given to the tumor cells by the ability of TNFα to promote EMT, and by similar (although to a lower extent) or other tumor-promoting activities of IL-1β (e.g. joint activities with other pro-malignancy elements)." (PMID 21486440, 2011). "Upon intravenous injection, GNP conjugated with TNF rapidly accumulates in tumor cells and is not detected in cells of the liver, spleen, and other healthy organs." (PMID 22649683, 2011). "In parallel, we determined the expression of CCL2, CCL5, TNFα and IL-1β in normal breast epithelial duct cells that were in proximity to the tumor cells in biopsies of patients with DCIS, IDC-no-relapse and IDC-with-relapse." (PMID 21486440, 2011). "In contrast, TNF-α did not modify the expression of a few set of genes known to be regulated by TNFα in tumor cells (such as MMP9)." (PMID 21754991, 2011). "The therapeutic benefit from TNF-α in ILP is thought to be not only due to its direct anti-proliferative effect, but also due to its ability to increase penetration of the chemotherapeutic agents into the tumor tissue." (PMID 22036896, 2011). "Serum IL-17, IFN-γ, and IL-4 levels were not detectable and serum TNF-α level was low in healthy mice in both groups, i.e. before tumor inoculation." (PMID 21484786, 2011). "TNFα and IFN-γ was up-regulated in activated primary and tumor-specific T cells." (PMID 21264227, 2011). "Relative to untreated MDA-MB-231 tumor xenografts, the xenografts from mice treated with UTI, TAX, and UTI+TAX showed decreased expression of IL-6, IL-8, and TNF-α proteins." (PMID 21345194, 2011). "Both Doxil and TNF-α showed limited therapeutic benefit when used as single agents, with no animal surviving beyond 50 days following tumor implantation." (PMID 21378416, 2011). "When looking at two groups separated by the median, there was a non-significant trend for improved survival with above median TNFα expression in the tumour islets (p = 0.15, not shown)." (PMID 20573209, 2010). "The cytotoxic function of non-dissociated NK-tumor cell conjugates remained very low and did not increase when supplemented with IL-2 although they proliferated and secreted higher amounts of TNF-α and IFN-γ in the supernatants." (PMID 20360990, 2010). "TNFα, a key proinflammatory factor, has been shown to have anti-tumor activity in several preclinical models and in non-comparative clinical trials." (PMID 20367887, 2010).
tumor (continued). "Additionally, a large amount of inflammatory cytokines, such as TNF-α, IL-2 and GM-CSF, are released by the activated CIK cells, which can directly inhibit tumor cells, or indirectly kill tumor cells by modulating the immune system." (PMID 20799994, 2010). "This suggests that TNFα is highly beneficial only when localized to macrophages and mast cells in tumour islets, and not when expressed by other cell types." (PMID 20573209, 2010). "One possible explanation might be that cytokines such as, TNF-α, IL-1β and VEGF produced from tumor microenvironment enhanced the expression of CXCR7." (PMID 20380740, 2010). "Besides, the different cytokines produced during inflammation (i.e., TNFα, IL1β, IL6, and IL8) can also activate several survival pathways, thus leading to an escape of tumor cells from cell death." (PMID 20339581, 2010). "A challenge with C. albicans (Ca-BTM group) did not change this picture: TNF-α increased during the first period of tumor progression, but there was a decrease at 72 h pi after the 14th day." (PMID 19534779, 2009). "Tumours often exhibit an inflammatory component and it may be possible under those conditions that VEGF could act in conjunction with TNFα to augment OPG levels." (PMID 19604388, 2009). "One is specific immunotherapy which targets particular antigens in MPM tissue, and the other is a non-specific, but anti-tumor immunotherapy using such cytokines as interleukin 2 (IL-2), tumor necrosis factor (TNF), and interferon (INF)." (PMID 19830126, 2009). "Contrary to our original expectation, TNF-α expression was neither detectable in infected tumor cells nor in colonized tumors." (PMID 19693266, 2009). "Our findings emphasize similarities between Gram-negative tumor-colonizing bacteria and tumor vascular disrupting agents and show the involvement of TNF-α in the initial phase of tumor-colonization by bacteria." (PMID 19693266, 2009). "Numerous factors, known to be present in the bone-tumor microenvironment, have been shown to induce MCP-1 secretion and gene expression including MCP-1 itself, TGF-β, tumor necrosis factor-alpha (TNF-α), parathyroid hormone related peptide (PTHrP) and various interleukins." (PMID 19192289, 2009). "Since depletion of TNF-α after i.v. administration of S. Typhimurium did not inhibit blood influx and bacterial tumor colonization completely, we suspected other pro-inflammatory cytokines to additionally support efficient bacterial tumor-colonization." (PMID 19693266, 2009). "Taken together, TNF-α is an important and effective factor in the initial phase of bacterial tumor-colonization, but it is probably not the only cytokine that is involved in bacterial entry into solid tumors." (PMID 19693266, 2009). "Neither single application nor combination of anti-FASL, anti-TRAIL and anti-TNF antibodies were able to substantially decrease the cytotoxic effect of virus-activated PBMCs towards tumor cells (data not shown)." (PMID 19125202, 2009). "Tumor progression also provoked alterations that changed the peritoneal macrophage profile: at the outset of the neoplastic process, BTM peritoneal macrophages demonstrated consistent TNF-α production and moderate IFN-γ and IL-10 production." (PMID 19534779, 2009). "Mock DCs were prepared by electroporation in the absence of tumor RNA followed by maturation with TNF-α and LPS." (PMID 18445282, 2008). "An increased migration of macrophages was also observed after stimulation of D5 tumor cells with IFN-γ (10 ng/ml) or TNF-α (35 U/ml) (data not shown)." (PMID 18001476, 2007). "Since therapeutic tumor-specific effector T cells secrete the type-1 cytokines IFN-γ and TNF-α, we determined whether chemokine expression by D5 was induced following stimulation with IFN-γ and TNF-α." (PMID 18001476, 2007).
tumor (continued). "This translated into a cytolytic activity against K562 cells with a median specific lysis of 26% at high effector cell numbers as determined by propidium iodide uptake, whereas IL-4/TNF-DC did not induce any tumor cell lysis (p = 0.006)." (PMID 17894866, 2007). "CTLs were neither able to produce IFN-γ and TNF-α nor lyse tumor cells that lacked the appropriate restriction element." (PMID 17592641, 2007). "The present experimental study was designed to assess whether metoclopramide administration has any effect on development of MNU-induced tumours, and evaluate the treatment of goserelin acetate on PRL, TNF alpha and NO expression." (PMID 18045456, 2007). "A significant negative correlation was found between systemic TNF-α levels and tumour cell proliferation (ρ=−0.697, P=0.01)." (PMID 16641913, 2006). "In our study, gene transcription of TNFα and IL-6 in white fat was not affected with tumour burden, in agreement with our previous report that their circulating levels were unchanged in cachectic mice." (PMID 17047651, 2006). "The original interest in TNF as a possible mediator of both innate immunity and disease pathogenesis in infectious disease came from analogies between the ability of BCG to protect against both tumours and intra-erythrocytic protozoa." (PMID 17029647, 2006). "Tumour rates of proliferation and apoptosis have a negative correlation with the CMI-associated cytokines TNF-α and IFN-γ while having a positive one with IL-10 (HI associated)." (PMID 16641913, 2006). "However, cytokine protein concentrations were significantly elevated in the tumour tissue: IL-1β 136 pg mg−1 of total protein (IQR 41–425), P=0.007; IL-6 3 pg mg−1 (IQR 0–46), P<0.05; IL-8 56 pg mg−1 (IQR 23–159), P=0.007; TNF-α 7 pg mg−1 (IQR 1–26), P<0.05." (PMID 17088911, 2006). "This phenomenon may be the result of an inflammatory process at the tumor site in which the cytokines released, such as IFN and TNF, induce MHC class II up-regulation." (PMID 17129373, 2006). "Inhibitory effects of tumour cell adhesion to HUVEC by endostatin are not likely to be explained by a direct effect of endostatin on TNF-α upregulation, since this pathway was observed not to be influenced by endostatin." (PMID 15700042, 2005). "The presence or lack of TNF-α-mediated synergy appeared to be independent of tumour size as also in smaller (diameter 3–4 mm) or bigger (7–8 mm) tumours comparable tumour responses were observed (data not shown)." (PMID 12610519, 2003). "Radiation alone (group 5), but not TNFα alone (group 2), significantly inhibited tumour progression as compared with the control group (P<0.00001)." (PMID 14612914, 2003). "In this perfusion setting, in which the dose of TNF-α is 20% of the dose used in ILP, an enhanced drug accumulation in tumour tissue might take place as well, as observed after TNF-α based ILP." (PMID 12610519, 2003). "Transient transfection of cathepsin-B (Cath-B) and -L (Cath-L) resulting in expression levels comparable to those found in many tumours did not sensitise tumour cells to TNF-α-mediated apoptosis." (PMID 14562034, 2003). "Studies involving regional or intratumoral injection of TNFα have demonstrated its potential for cancer therapy, but only when a high enough therapeutic concentration of TNFα was obtained in the tumour with a nontoxic systemic concentration." (PMID 14612914, 2003). "TNFα usually does not kill untransformed cells but shows an antiproliferative effect on certain tumour cells in vitro by still undefined mechanisms." (PMID 14612914, 2003). "In all, 16.7% of patients with TNF+488A and 29.9% of patients without TNF+488A presented with a G1 tumour (P=0.015)." (PMID 12966432, 2003). "After IHP with TNF-α however a more than 5-fold increase of melphalan in tumour tissue is measured compared to tumour tissue after IHP without TNF-α; (P<0.05)." (PMID 12610519, 2003).
tumor (continued). "TNF-α and CD95L play a crucial role in the activation induced cell death (AICD) of mature T cells whereas TRAIL has been shown to induce apoptosis mainly in tumour cells but also in normal human hepatocytes, astrocytes and keratinocytes." (PMID 11875749, 2002). "DMXAA increased tumour necrosis factor (TNF) concentrations in plasma of both tumour bearing and non-tumour bearing mice." (PMID 12085190, 2002). "In conclusion, isolated limb perfusion with actinomycin D and TNF results in a tumour response of 40% which is not better than the standard ILP with melphalan plus TNF." (PMID 11953868, 2002). "We evaluated the anti-tumour effect of actinomycin D and melphalan with or without TNF after an isolated limb perfusion." (PMID 11953868, 2002). "In vitro TNF-α fails to augment drug uptake in tumour cells or to increase cytotoxicity of the drug." (PMID 10732774, 2000). "We found a significant sixfold increase in melphalan tumour tissue concentration after ILP when TNF-α was added to the perfusate, which provides a straightforward explanation for the observed synergism between melphalan and TNF-α in ILP." (PMID 10737379, 2000). "In vivo isolated kidney perfusion, with TNF-α alone or in combination with melphalan, did not result in a significant anti-tumour response in either tumour model in a subrenal capsule assay." (PMID 10027309, 1999). "We conclude that, because of the susceptibility of the kidney to perfusion with TNF-α, the minimal threshold concentration of TNF-α to exert its anti-tumour effects was not reached." (PMID 10027309, 1999). "In comparison to oxygenated ILP, hypoxia was shown to enhance anti-tumour activity of melphalan alone and TNF alone but not of their combined use." (PMID 10389992, 1999). "In contrast, FAA caused no induction above that of control levels and in some cases suppressed expression relative to controls, extending previous data that DMXAA but not FAA up-regulates TNF mRNA in the human HL-60 tumour cell line." (PMID 9413946, 1997). "We concluded that regional liver treatment resulted in a relatively high local level of TNF-alpha, but also that this cytokine did not preferentially accumulate in tumour tissue." (PMID 9166943, 1997). "The mechanisms of the reported in vivo synergistic anti-tumour effects of TNF-alpha and melphalan are not precisely understood." (PMID 8980389, 1996). "mRNA expression of interleukin (IL)-1 alpha, IL-6, IL-8, interferon (IFN)-gamma, and tumour necrosis factor (TNF)-alpha was observed in untreated tumour tissues, which were not enhanced by cyclophosphamide treatment." (PMID 8688335, 1996). "We found that there was significant TNF-alpha and IL-1 beta release during ADCC mediated by each of these three antibodies and that the magnitude of cytokine release seemed to reflect the degree of tumour cell lysis produced by each antibody." (PMID 7669568, 1995). "Expression of TNF-alpha or TNF-R p75 was not detectable in normal breast tissue or in non-malignant breast tissue adjacent to the tumours." (PMID 7519867, 1994). "Neither intact MAb 32 nor FAb' fragments of MAb 32 showed any tumour regressive activity in the absence of TNF alpha." (PMID 1377483, 1992). "Treatment with either rHu-TNF or rat IFN-gamma given individually did not affect the overall rate of tumour growth (P = 0.157 and 0.40 respectively) although an initial reduction in tumour size was observed during the first few days after injection." (PMID 2495016, 1989). "Both tumour and non-tumour-bearing animals responded with a similar elevation of their serum TNF levels 90 min after a single injection of endotoxin." (PMID 3390373, 1988). "Using vaccinia virus and EL4 tumor models expressing the same antigen, we found that Tum-CD8+ cells displayed a distinct phenotype, including sustained expression of inhibitory receptors (PD-1, TIM-3), altered integrin expression, and reduced production of IFNγ and TNF." (PMID 42023146, 2026).